HMGA2 (high mobility group AT-hook 2)
Diseases named in the same sentence as HMGA2 in open-access papers (continued):
Sharing a sentence is not in itself a finding about the gene and the disease.
retinoblastoma (10 papers, 2006 to 2025). A malignant tumor that originates in the nuclear layer of the retina. "Second, the gene expression profiles from HMGA2 knockdown of human retinoblastoma (RB) Y79 cells were derived from the GEO dataset (GSE31687)." (PMID 31684108, 2019). "Based on the striking mirror similarities between the phenotypes of pRB and HMGA2 animal models, our group has recently investigated a potential functional interaction between HMGA2 and the Retinoblastoma protein." (PMID 16914062, 2006). "Since HMGA2 promotes retinoblastoma cell proliferation and regulates DNA damage response, these findings suggest that DOT1L inhibition plays a dual role in chemosensitizing retinoblastoma cells by impairing early DNA damage response and downregulating HMGA2 expression." (PMID 38672640, 2024). "We observed the hyperphosphorylation of HMGA2 at Ser101 and Thr150 in retinoblastoma." (PMID 29914080, 2018). "Additionally, the non-histone chromosome protein HMGA2 was identified as a novel target gene of DOT1L in retinoblastoma cells, with its expression epigenetically upregulated by DOT1L." (PMID 38672640, 2024).
rhabdomyosarcoma (10 papers, 2016 to 2025). A rare aggressive malignant mesenchymal neoplasm arising from skeletal muscle. "We further observed analogous expression of IGF2BP2, an oncofetal protein and downstream target of HMGA2 in 100% of human LAM and TSC lesions, similar to the gene’s pattern of co-expression with HMGA2 in rhabdomyosarcoma and during myoblast proliferation." (PMID 32365712, 2020). "Both RPSAP52 isoforms were abundantly expressed in most rhabdomyosarcoma cell lines, with just one order of magnitude higher HMGA2 expression in Rh28, Rh41, or CW9019 cells." (PMID 31484926, 2019). "Additionally, a novel RAB3IP–HMGA2 fusion transcript has been identified in adult rhabdomyosarcoma of the head and neck, suggesting potential diagnostic and therapeutic implications as RAB3IP is associated with cellular proliferation, and HMGA2 with increased metastasis rate and poor prognosis." (PMID 40981124, 2025). "In endogenous producers (HT1080/C1 fibrosarcoma transfectants with doxycycline (dox) regulated shHMGA2 expression and RD rhabdomyosarcoma cells) and the HMGA2 transfectants of undifferentiated thyroid carcinoma cells UTC8505, HMGA2 was exclusively detected in nuclear protein extracts." (PMID 26799419, 2016).
squamous cell carcinoma (10 papers, 2016 to 2025). A carcinoma arising from squamous epithelial cells. "At the protein level, 90 % of the squamous cell carcinomas expressed high levels of the HMGA2 protein compared to 47 % of the adenocarcinomas (p < 0.0001)." (PMID 26858029, 2016). "In histological subsets, 90 % of the squamous cell carcinomas expressed high levels of HMGA2, while 47 % of the adenocarcinomas showed high expression of the protein; this difference was highly significant (p < 0.0001)." (PMID 26858029, 2016). "A significant difference in HMGA2 mRNA expression between the histological subtypes of NSCLC was seen with a higher expression in the squamous cell carcinomas." (PMID 26858029, 2016). "Compared to adenocarcinomas, squamous cell carcinomas had a median 5-fold increase in mRNA expression of HMGA2 (p = 0.003)." (PMID 26858029, 2016). "Close to all squamous cell carcinomas expressed high levels of HMGA2 compared to 46 % of the adenocarcinomas, and this difference was highly significant." (PMID 26858029, 2016). "We discovered a significant difference in the median values of HMGA2 mRNA expression according to tumour histology (p = 0.003) with a considerably higher median fold change value in the squamous cell carcinoma group (70.6 fold) compared to adenocarcinomas (13.1 fold) and others (5.8 fold)." (PMID 26858029, 2016). "In our study, analysis of fresh-frozen NSCLC tumour tissue by RT-qPCR revealed a significant difference in HMGA2 mRNA expression in histological subsets; with an elevated median expression value in the squamous cell carcinomas of approximately 5-fold over the median value of adenocarcinomas." (PMID 26858029, 2016). "The more benign histology of carcinoids lacked HMGA2 expression, while among squamous cell carcinomas, most samples showed high expression." (PMID 26858029, 2016).
thyroid tumor (10 papers, 2011 to 2025). A benign or malignant neoplasm affecting the thyroid gland. "The expression levels of HMGA2 and PLAG1 are highly correlated in thyroid tumors, and HMGA2 overexpression in cellular models is associated with an increase in PLAG1 expression." (PMID 35741015, 2022). "The association of HMGA2 mRNA upregulation with malignancy of thyroid tumors has been demonstrated in several publications." (PMID 31660895, 2019). "Total nucleic acids extracted from dried FNA smears were analyzed for five somatic point mutations and two translocations typical of thyroid tumors as well as for relative concentrations of HMGA2 mRNA and 13 microRNAs and the ratio of mitochondrial to nuclear DNA by real-time PCR." (PMID 31660895, 2019). "Previously, we pointed out GABRB2 and HMGA2 as potential diagnostic makers in thyroid tumors." (PMID 28469731, 2017). "Our previous observations in human PTC are closely thus recapitulated in a mouse model of PTC and opens new research perspectives to delineate the role of miR-204-5p and HMGA2 in thyroid tumor development." (PMID 37445942, 2023). "As it was pointed above, expression of HMGA2 correlates with malignant penotype of thyroid tumors and can be used as a tool to differentiate malignant from benign lesions." (PMID 25887408, 2015). "Furthermore, in thyroid tumors THADA mRNA expression was found to be inversely correlated with HMGA2 mRNA." (PMID 22050638, 2011). "Spearman’s correlation coefficient thus was calculated as a measure of association between the HMGA2 and PLAG1 expression for all 37 tumor samples and resulted in a high value (ρ = 0.82, p<0.0001) indicating that the expression of both genes is strongly correlated in thyroid tumors." (PMID 24516594, 2014). "The expression of HMGA2 and PLAG1 was quantified in 37 thyroid tumors." (PMID 24516594, 2014). "Overall, our findings suggest that HMGA2 plays a significant role in the dedifferentiation of PTC cells in response to the stimulation of the MAPK cascade or to the inhibition of the cAMP-dependent signalling pathway and subsequently, contributes to the aggressiveness of thyroid tumors." (PMID 40004107, 2025).
pancreatic adenocarcinoma (9 papers, 2014 to 2025). "In their study including 14 patients with pancreatic adenocarcinoma, Watanabe et al7 observed that HMGA2 and vimentin expression increased while E-cadherin expression decreased using Western blot analysis when the RAS/MEK pathway was inhibited." (PMID 37787719, 2023). "Our study is similar to the literature and supports that HMGA2 is a useful molecular marker in the differential diagnosis of pancreatic adenocarcinoma." (PMID 37787719, 2023). "Our study first found the different expression of HMGA2 in tumor differentiation of pancreatic adenocarcinoma." (PMID 29596435, 2018). "Finally, 8 differentially expressed genes (ERLIN1, HMGA2, FAM110B, EGFR, MCM2, BCL2L1, E2F1 and RAC1) were considered to be significantly negatively associated with survival (P < 0.05) time of pancreatic adenocarcinoma patients." (PMID 29596435, 2018). "In addition, we also found that HMGA2 was significantly related to the survivability of pancreatic adenocarcinoma." (PMID 29596435, 2018). "Thus, we supposed that HMGA2 was a promising molecular target for pancreatic adenocarcinoma therapy and prognosis." (PMID 29596435, 2018). "The activation of TGF-β signaling induced by HMGA2 was shown to occur preferentially at the invasive front of colorectal tumors and in secondary metastatic lesions, and in lymph node metastasis of pancreatic adenocarcinoma." (PMID 24733089, 2014). "At the time of analysis, most KP172CT;Hmga2+/+ and KP172CT;Hmga2CK/CK animals had developed pancreatic adenocarcinoma." (PMID 30228296, 2018). "Previous reports have shown that MSI2 regulates the 3’UTR of HMGA2 in pancreatic adenocarcinoma, but based on our results from luciferase reporter assays, the MSI2 promoter region is directly bound by HMGA2, and knockdown or overexpression of MSI2 expression did not affect HMGA2 expression." (PMID 31053152, 2019).
papillary thyroid cancer (8 papers, 2014 to 2025). "Indeed, we demonstrated the involvement of HMGA2 in cell invasion and its direct regulation by miR-204-5p, a microRNA identified in papillary thyroid carcinoma as downregulated and inversely associated with aggressiveness." (PMID 40004107, 2025). "The prognostic impact of high HMGA2 expression was markedly lower in 282 papillary carcinomas (p = 0.0176)." (PMID 40518465, 2025). "In papillary thyroid carcinoma, a reduced miR-98-5p level was detailed to correspond with elevated HMGA2 expression, which subsequently affects cell growth and apoptosis, emphasizing the regulatory role of miR-98-5p on HMGA2." (PMID 38872210, 2024). "HMGA2 IHC may be especially useful in thyroidal cytology, where the sensitivity is only 40–95% for recognizing papillary carcinomas and 42–83% in follicular carcinomas." (PMID 40518465, 2025). "In our study, 91% of papillary thyroid carcinomas, 61.3% of follicular carcinomas, and 61.1% of follicular adenomas were HMGA2 positive, but none of eight normal thyroid samples." (PMID 40518465, 2025). "Akin to HMGA2, PLAG1 is also expressed at higher levels in papillary carcinomas." (PMID 24516594, 2014). "Moreover, treatment of TPC-1 and BCPAP cells for 24 h with trametinib, a MEK inhibitor which was shown to reduce HMGA2 mRNA expression levels, increased TG, TPO and PAX8 mRNA levels, suggesting that the MAPK pathway induces cell dedifferentiation in papillary thyroid carcinomas through HMGA2." (PMID 40004107, 2025).
gallbladder cancer (7 papers, 2012 to 2020). "Downregulation of HMGA2 by hsa-miR-26a negatively affects cell proliferation and has tumour suppressive effects in gall bladder cancer." (PMID 29703144, 2018). "A previous study showed that HMGA2 mRNA levels were inversely correlated with miR-26a expression and that reduced levels of HMGA2 inhibited the proliferation of gallbladder cancer cells." (PMID 29311920, 2017). "HMGA2 also reflected progression and clinical behaviors of gallbladder cancer and was an important biological marker of prognosis." (PMID 22613496, 2012). "Furthermore, high mobility group AT-hook 2 (HMGA2) was found to be the direct target of miR-26a in gallbladder cancer in which HMGA2 mRNA levels and miR-26a levels were negatively correlated." (PMID 26040010, 2015). "Cox multivariate regression analysis showed that the HMGA2 positive expression and/or CD9 negative expression was an important indicator reflecting the poor prognosis of gallbladder cancer." (PMID 22613496, 2012).
Infertility (7 papers, 2018 to 2024). "Mice homozygous for a null HMGA2 allele present a “superpygmy” phenotype, reduced amounts of fat tissue and infertility." (PMID 30581455, 2018). "In mice, the loss of both alleles of HMGA2 leads to infertility." (PMID 38254930, 2023). "Inactive HMGA2 has been shown to result in smaller sizes and lower organ weights, as well as infertility and abnormal testicular descent." (PMID 35617214, 2022). "A plausible explanation might be that overexpression of HMGA2 merely reflects abnormalities in cell differentiation and maturation; alternatively, the abnormal proliferation might be a phenotype in the course of PCOS, not a direct cause of infertility." (PMID 39025980, 2024).
neuroblastoma (7 papers, 2000 to 2024). Neuroblastoma (NB) is the most common solid, extracranial childhood tumor. "During pathology at the multicentric level, HMGA2 gene rs8756 A>C polymorphism has been linked to a reduced risk of neuroblastoma in Chinese children." (PMID 39404397, 2024).
serous carcinomas (7 papers, 2012 to 2024). "High-grade serous carcinoma was associated with greater HMGA2 expression compared to endometrioid OC." (PMID 22235203, 2012). "Three T samples with the highest HMGA2 expression derived from patients with: clear cell adenocarcinoma, endometrioid adenocarcinoma, and serous carcinoma." (PMID 36140779, 2022). "Accordingly, Wei and colleagues showed that HMGA2 is highly expressed in endometrium serous carcinomas (about 90% of the samples evaluated were positively stained for HMGA2), whereas it is absent in 60% of the EEC samples assessed." (PMID 31096664, 2019). "Although IMP2 and HMGA2 are frequently expressed in serous carcinomas 20,26, there are insufficient data about their expression in clear cell carcinoma." (PMID 30550483, 2019). "Fourteen consecutive endometrioid OC were analyzed and twelve consecutive high-grade serous carcinomas were analyzed for HMGA2 expression by immunohistochemical staining." (PMID 22235203, 2012). "The expression of high-mobility group AT-hook 2 (HMGA2) was compared in 68 grade 3 endometrioid carcinomas and 71 serous carcinomas using tissue microarrays." (PMID 30550483, 2019).
diabetes (6 papers, 2012 to 2025). "Variants at PLCE1 and HMGA2 were significantly associated with hypertension, diabetes, and anthropometric traits, such as body fat mass and waist circumference." (PMID 34127677, 2021). "We then examined whether the expression of HMGA2, PPARG, ADIPOQ and IL6 was associated with diabetes remission." (PMID 40740163, 2025).
dwarfism (6 papers, 2020 to 2025). "However, some major loci remained, including alleles that determine monogenic forms of dwarfism, such as the deleted HMGA2 form." (PMID 40607659, 2025). "In rabbits, a deletion at the HMGA2 locus caused dwarfism and altered craniofacial development." (PMID 37239396, 2023). "A variant in HMGA2 was previously reported to be correlated with body weight in chicken, but our study is the first to report the association between HMGA2 and chicken dwarfism." (PMID 33897823, 2021). "We report bantam‐associated genes in these group‐based studies, including HMGA2 and PRDM16, some of them are reported to correlate with dwarfism in chicken for the first time." (PMID 33897823, 2021). "Interestingly, HMGA2 deletion in rabbits resulted in dwarfism (small stature being a common phenotype in diseases of impaired ribosome biogenesis) and altered craniofacial development." (PMID 32813698, 2020). "While a large deletion in the HMGA2 gene is a major locus associated with dwarfism in Netherland Dwarf rabbits, it may not fully explain the reduced body size in this breed or other dwarf breeds." (PMID 40607659, 2025). "No signal in the HMGA2 gene region was identified in the dwarf/small body size breeds that we analysed in our study, although a large deletion that overlaps the promoter region and the first three exons of this gene has been reported to be the causative mutation of a form of dwarfism." (PMID 35062866, 2022).
metastatic disease (6 papers, 2003 to 2023). "A serum HMGA2 was repeated and it expressed in 7 of 9 patients at this stage further confirming a role of HMGA2 in predicting metastatic disease." (PMID 33639654, 2021). "We have previously shown that TNBCs are active for oncogenic Wnt10b/β-catenin signaling and that WNT10B ligand and its downstream target HMGA2 are predictive of poorer outcomes and are strongly associated with chemoresistant TNBC metastatic disease." (PMID 29281678, 2017). "However, there was a significant difference in HMGA2 tissue expression between patients with metastatic disease and those with primary localized tumor (P = 0.0165)." (PMID 35388973, 2022). "Notably, HMGA2 and IL20RB were more highly expressed in metastatic tumors than in primary tumors, consistent with the trend observed for GRIN2D expression." (PMID 37553583, 2023). "Out of 74 patients who did not have HMGA2 expression in plasma initially, 9 patients presented with metastatic disease during follow up." (PMID 33639654, 2021).
pulmonary fibrosis (6 papers, 2019 to 2024). Chronic progressive interstitial lung disorder characterized by the replacement of the lung tissue by connective tissue, leading to progressive dyspnea, respiratory failure, or right heart failure. "This study has demonstrated for the first time that let-7d was sufficient to attenuate the effects of silicosis on pulmonary fibrosis through the repression of its target HMGA2 in A549 cells." (PMID 35519367, 2019). "Since miRNA let-7d has been demonstrated as a direct regulator of HMGA2, we first analyzed their expression in a silica-induced pulmonary fibrosis mouse model." (PMID 35519367, 2019). "An interesting study has evidenced that, in mice exposed to silicone to induce pulmonary fibrosis, an overexpression of miRNA let-7d led to a reduction in HMGA2 expression and inhibition of EMT; while the suppression of miRNA let-7d augmented HMGA2 expression and triggered silica-induced EMT." (PMID 38474021, 2024). "In conclusion, let-7d negatively regulated silica-induced EMT and inhibited silica-induced pulmonary fibrosis, which might be partially realized by directly binding to HMGA2." (PMID 35519367, 2019). "HMGA2 (High-mobility group AT-hook 2) is a transcription factor that is induced by the TGF-β1/Smad3 signaling pathway and is also reported to be upregulated in pulmonary fibrosis and inhibit bleomycin-induced pulmonary fibrosis." (PMID 35980387, 2022). "The lack of HMGA2 expression in similar proliferative interstitial lung diseases to LAM, like interstitial pneumonitis and pulmonary fibrosis, also suggests that HMGA2 misexpression transforms tumor cells in LAM, and is not solely due to an abnormal increase in cell proliferation rates." (PMID 32365712, 2020).
renal cell carcinoma (6 papers, 2016 to 2026). "A high expression of HMGA2 in human renal cell carcinoma (RCC) is related with tumor invasiveness and poor prognosis." (PMID 35439951, 2022). "Further characterization of the functional correlation between HMGA2 and HMGA2-mediated EMT target gene regulation will help us understand the tumorigenesis of renal cell carcinoma." (PMID 35439951, 2022). "Early studies from our lab showed that HMGA2 is significantly overexpressed in CCRCC specimens of patients and RNAi silencing of HMGA2 gene in cultured renal cell carcinoma (RCC) ACHN cells resulted in decreased cell ability of proliferation and invasion." (PMID 35439951, 2022). "In addition, in renal cell carcinoma cells in vitro, overexpression of HMGA2 facilitated the EMT process through the TGFβ/SMAD2 signaling pathway." (PMID 38361784, 2024). "Based on these observations, up-regulation of HMGA2 and CTHRC1, together with loss of CDKN2A, may serve as prognosis markers in renal cell carcinoma." (PMID 27144525, 2016). "HMGA2 is a non-canonical epigenetic transcription regulator physiologically expressed in the developing embryonic tissues but ectopically expressed in various human malignancies including renal cell carcinoma." (PMID 35439951, 2022).
brain tumors (5 papers, 2015 to 2020). "Furthermore, xenografted brain tumors derived from HMGA2-depleted GICs contained much fewer vascular structures." (PMID 27259253, 2016). "Brain tumor allograft sections derived from mouse GFP+ green fluorescent NF53 brain tumor‐initiating cells showed expression of HMGA2 and stem cell marker nestin in GFP+ NF53 brain tumor cells." (PMID 28500786, 2017).
clear cell renal cell carcinoma (5 papers, 2018 to 2025). "The prognostic role of HMGA2 upregulation was particularly strong in clear cell renal cell carcinoma (ccRCC)." (PMID 40518465, 2025).